IGLV3-9 (immunoglobulin lambda variable 3-9)
Description:
V region of the variable domain of immunoglobulin light chains that participates in the antigen recognition. Immunoglobulins, also known as antibodies, are membrane-bound or secreted glycoproteins produced by B lymphocytes. In the recognition phase of humoral immunity, the membrane-bound immunoglobulins serve as receptors which, upon binding of a specific antigen, trigger the clonal expansion and differentiation of B lymphocytes into immunoglobulins-secreting plasma cells. Secreted immunoglobulins mediate the effector phase of humoral immunity, which results in the elimination of bound antigens. The antigen binding site is formed by the variable domain of one heavy chain, together with that of its associated light chain. Thus, each immunoglobulin has two antigen binding sites with remarkable affinity for a particular antigen. The variable domains are assembled by a process called V-(D)-J rearrangement and can then be subjected to somatic hypermutations which, after exposure to antigen and selection, allow affinity maturation for a particular antigen.
Synonyms: IGLV39; V2-6
Gene: Immunoglobulin variable (V) gene on chromosome 22 (22,819,010 to 22,819,756, forward strand). Ensembl gene ENSG00000211670.
Subcellular location: Secreted; Cell membrane
Gene Ontology:
Biological process: immune response
Cellular component: extracellular region; immunoglobulin complex; plasma membrane
Homologues: Orthologues: macaque IGLV3-9 (74% identical), tropical clawed frog igl (63% identical). Paralogues in human: IGLV3-12 (86% identical), IGLV3-21 (86% identical), IGLV3-1 (77% identical), IGLV3-10 (71% identical), IGLV3-25 (71% identical), IGLV3-16 (70% identical), IGLV3-19 (68% identical), IGLV3-27 (68% identical), IGLV3-22 (67% identical), IGLV3-32 (64% identical), IGLV1-40 (63% identical), IGLV2-18 (61% identical), and 81 more.